IFNG (interferon gamma)
Diseases named in the same sentence as IFNG in open-access papers (continued):
Sharing a sentence is not in itself a finding about the gene and the disease.
neurodegenerative disease (38 papers, 2013 to 2026). A disorder of the central nervous system characterized by gradual and progressive loss of neural tissue and neurologic function. "Chronic low-grade inflammation, characterized by continuous production of pro–inflammatory cytokines like TNFα, IL–1, IL–6, and interferon-gamma (IFNγ), is associated with neuroinflammation, a key feature of neurodegenerative diseases." (PMID 39940416, 2025). "In recent years, interferon gamma, cytokines, risk factors, working memory, interleukin-6, older adults, and neurodegenerative diseases have emerged as the strongest citation burst keywords." (PMID 40791247, 2025). "Apart from revealing the inhibition of important genes implicated in neurodegenerative diseases in cultured microglial cells treated with LPS or LPS + IFNγ, the present RNA-Seq analysis also allowed us to gain further understanding of how both stimuli affect microglial gene expression." (PMID 30382133, 2018). "This suggests that immune regulators such as interferon gamma and interleukin-6, among other cytokines, may serve as risk factors for cognitive function in the elderly population and are closely related to the onset and progression of neurodegenerative diseases." (PMID 40791247, 2025). "LRRK2–PD microglia as well as microglia from other neurodegenerative diseases additionally displayed increased phagocytic activity, paralleling our finding in IFNγ treated SPG11 iMGL." (PMID 38305941, 2024). "It is now well recognized that brain aging, traumatic brain injury and neurodegenerative diseases lead to the formation of primed microglia, while the proinflammatory cytokine IFNγ has been identified as a microglial priming factor." (PMID 27598576, 2016). "Consequently, enhanced IFNγ concentrations have been found in the aged brain, following traumatic brain injury and at early stages of neurodegenerative diseases, including Alzheimer’s disease, Parkinson’s disease and vascular dementia." (PMID 27598576, 2016). "However, IFNγ is also expressed in many neurodegenerative disease states where alterations in NSPC function are also observed." (PMID 27178303, 2016). "Additionally, IFNγ is also produced by microglial cells in the CNS during infectious and neurodegenerative diseases." (PMID 25695249, 2015). "These pathways were, in general, shared across all neurodegenerative diseases, even though the major overlap was found for the synaptic functions (BDNF, CCL2, ACHE, GFAP, NEFH or NEFL) and microglia pathways (TREM2, IL13, IL6R IFNG)." (PMID 41250190, 2025). "Furthermore, increased expression of proinflammatory cytokines such as IL-6, IL-1β, and TNFα that we detected in IFNγ treated SPG11 iMGL, was also described for iPSC-derived microglia from patients with other neurodegenerative diseases, including PD and ALS." (PMID 38305941, 2024). "Like other neurodegenerative diseases, PD also involves elevated levels of proinflammatory cytokines monocyte chemoattractant protein-1 (MCP-1), CCL-5, macrophage inflammatory protein-1α (MIP-1α), IL-8, interferon-gamma (IFNγ), IL-1β, and TNFα." (PMID 23840922, 2013). "While EVs from both 14 and 21 DIV cultures reduced slightly the secretion of the cytokines IFNγ and IL-1a, only EVs from 14 DIV cultures decreased the levels of IL-6, a cytokine predominantly released in neurodegenerative diseases through EVs in the CNS and involved in astrogliosis." (PMID 35163295, 2022).
metabolic disease (35 papers, 2012 to 2026). A congenital disorder (due to inherited enzyme abnormality) or acquired (due to failure of a metabolically important organ) disorder resulting from an abnormal metabolic process. "The IFNγ-inducible TRY-KYN inflammatory cascade helps to understand the association between inflammation and metabolic disorders, which is now recognized as a crucial mechanism in the development of MetS." (PMID 30862026, 2019). "Using the random-walk method, we defined a set of genes as a human disease module for each of the cardiovascular and metabolic diseases, and IFNγ-related diseases." (PMID 27796300, 2016). "Embryotoxic cytokines, such as tumor necrosis factor (TNF), TNF-related apoptosis-inducing ligand (TRAIL), and interferon-gamma (IFN-γ), could participate in the programming of fetal growth restriction or development of metabolic disorders." (PMID 38612572, 2024). "IFNγ also contributes to microbial control during metabolic disease." (PMID 33972511, 2021). "The hypothesis of the IFNγ inducible TRY-KYN inflammatory cascade helps to understand the increased association between aging, inflammation, and metabolic disorders." (PMID 30862026, 2019). "However, a disparity in the KYN level, as well as the relationship between the carrier of the A/T genotype of the IFNγ gene and the higher level of KYN in the group of women with MetS, may indicate a significant association between inflammation, metabolic disorders, and TRY-KYN inflammatory cascade." (PMID 30862026, 2019). "Activated MAIT cells exhibit T helper 1 (Th1)/Th17 secretion patterns, such as interferon gamma (IFNγ), tumor necrosis factor alpha (TNF-α), and IL-17, and may be involved in the pathogenesis of various inflammatory diseases and metabolic diseases." (PMID 36499635, 2022).
respiratory disease (35 papers, 2011 to 2025). "Expression levels for CXCL10 and IFNG were 4.8 and 2.6 times higher, respectively, in the vaccinated animals, most likely due to two animals with mild symptoms of non-respiratory disease in the vaccinated group." (PMID 35062765, 2022). "Notably, aspirin is known to induce aspirin-exacerbated respiratory disease (AERD), in which IFNγ plays a crucial role." (PMID 34741187, 2021). "Therefore, the strongly correlated IFNγ and CCL20 may mark a circulating readout of severe respiratory disease complications." (PMID 34957382, 2022).
adenocarcinoma (33 papers, 2007 to 2025). A common cancer characterized by the presence of malignant glandular cells. "Beyond PD-L1 expression, a 6-gene interferon gamma (IFNγ)-related signature based on gene expression profiling was tested in a small population of pembrolizumab-treated patients with G/GEJ adenocarcinoma (N = 33)." (PMID 35778636, 2022). "The group of infiltrating adenocarcinomas showed a lower expression of IFNγ than the in situ group, and a similar expression to that observed in the benign disease group." (PMID 17697357, 2007).
renal disease (33 papers, 2006 to 2025). "This IFNγ related immune response has been demonstrated to be associated with various kidney diseases." (PMID 28425456, 2017). "IL-10 can inhibit kidney disease in lpr mice through preventing IFNγ-mediated production of IgG2a, a major immune deposit in the kidney of these mice." (PMID 28697806, 2017). "Depletion of IFNγ significantly improved renal disease induced by pristane, with reduction in the production of the anti-DNA/chromatin autoantibody." (PMID 28982388, 2017). "The dual presence of IgG2a and IgG3 antibodies in affected kidneys suggests the possible importance of interferon gamma in the pathogenesis of the kidney disease, as this cytokine can enhance production of antibodies of both subclasses." (PMID 22248284, 2012). "Elevated in both human and experimental kidney diseases, MCP1 secretion is triggered by interleukin-1, tumour necrosis factor-alpha and interferon-gamma, all of which were induced in our model by TGFβ1, yet blocked when co-applied with danegaptide." (PMID 33802083, 2021).
heart disease (31 papers, 2008 to 2025). "Finally, we show that 11 GWAS risk variants for 8 common cardiac diseases overlap IFNγ-upregulated ATAC-seq peaks." (PMID 40104808, 2025). "We also show that GWAS variants for 8 cardiac diseases overlap ATAC-seq peaks that are only present after IFNγ treatment, suggesting that they may capture context-specific regulatory variants." (PMID 40104808, 2025). "Genetic variants in risk loci associated with cardiac diseases were intersected with ATAC-seq peaks to evaluate whether they were in chromatin that is only accessible after IFNγ treatment." (PMID 40104808, 2025). "•GWAS cardiac disease variants are found in IFNγ-induced active chromatin." (PMID 40104808, 2025). "Finally, we show that 8 IFNγ-upregulated ATAC-seq peaks overlap 11 GWAS variants for 8 cardiac diseases, suggesting that certain GWAS loci may capture context-specific regulatory variation that are only active after IFNγ stimulation." (PMID 40104808, 2025). "Systemic inflammatory profile, enriched in NO and cytokines such as tumor necrosis factor (TNF) and interferon-gamma (IFNγ), is detected in CD patients and in experimental chronic T. cruzi infection related with the severity of cardiac disease." (PMID 41237192, 2025). "Most efforts to understand the role of IFNγ in cardiac disease pathologies have relied on mouse models because obtaining primary cardiac tissues from patients is difficult and often not possible." (PMID 40104808, 2025). "Inflammatory cytokines play a central role in the pathophysiology of many cardiac diseases, with interferon gamma (IFNγ) emerging as a key modulator of the inflammatory response." (PMID 40104808, 2025). "Our findings reveal insights into IFNγ-induced activation of an immune-like regulatory network in human cardiac tissue and the potential role that regulatory elements in this pathway play in common cardiac diseases." (PMID 40104808, 2025). "Our model used IFNγ treatment to mimic cytokine release by immune cells, however, future in vivo studies could better model the role of IFNγ in cardiac disease in the context of an intact immune system." (PMID 40104808, 2025). "Therefore, we tested the subtypes of Th1 (CD4+IFNγ+), Th2 (CD4+IL4+), and Treg (CD4+CD25+Foxp3+) cells, which influence inflammation associated with heart disease." (PMID 31547872, 2019). "The main finding of this study is that sildenafil in human cardiomyocytes inhibited protein and gene expression of IFNγ + TNFα-induced chemokine CXCL10 (IC50 2.6 × 10−7 M), which is a critical trigger of early Th1 immune/inflammatory response during cardiac diseases." (PMID 27165639, 2016). "Studies on the specific role of cytokines in the immune response against T. cruzi have been recently reported and demonstrate that large amounts of Th1 pro-inflammatory cytokines such as Interferon Gamma (IFN-γ), Tumor Necrosis Factor Alpha (TNF-α) are related to cardiac disease." (PMID 24608170, 2014).
psychiatric disorder (18 papers, 2016 to 2025). A disorder characterized by behavioral and/or psychological abnormalities, often accompanied by physical symptoms. "Excessive secretion of interferon-gamma in the periphery and the brain triggers inflammatory cascades involved in aging and aging-related medical and psychiatric disorders." (PMID 35958162, 2022).
inflammatory myopathies (16 papers, 2013 to 2025). "In this study, we define the specific transcriptomic features of GM, revealing a distinct activation of the IFNγ pathway compared to other myopathies, as well as an increase in multiple proinflammatory cytokines, including IL1B, TNF, and TGFB1." (PMID 40568658, 2025). "A range of inflammatory cytokines are found upregulated in sIBM compared to healthy muscle or other inflammatory myopathies, including interferon γ (IFNγ), tumor necrosis factor α (TNFα), interleukin (IL)-7, and IL-32." (PMID 37731843, 2023). "Transcription of the guanylate-binding protein 6 (GBP6) gene, which is induced by IFNγ signaling, was seven times higher in sIBM compared to controls or other inflammatory myopathies." (PMID 37731843, 2023). "Notably, IFNγ transcripts are elevated in sIBM compared to control and other inflammatory myopathies." (PMID 37731843, 2023). "A study on anti-synthetase myopathy showed that the HLA-DR expression is correlated with CD8+ T cell infiltration, which suggests an involvement of the interferon-gamma pathway in the myofiber HLA-DR expression." (PMID 35683408, 2022).
gastrointestinal tumors (14 papers, 2010 to 2026). "Preliminary experiments with CNBs from lung, kidney, and gastrointestinal tumors revealed cytokine induction patterns unique to individual specimens, particularly in IFNγ and CXCL10." (PMID 40791544, 2025). "Administration of anti-granulocyte colony-stimulating factor antibodies suppressed the colon carcinogenesis and significantly increased the levels of NK cells and IFNγ-producing CD4+ and CD8+ T cells." (PMID 28861089, 2017). "Also, IL-10 was significantly decreased with IFNγ or IL-17A treatments, suggesting a decrease in inhibitory factors concomitant with an increase in cytotoxicity in two GI tumor models." (PMID 33042110, 2020). "In conclusion, we report previously unrecognized pro-tumorigenic roles for G-CSF in gastrointestinal tumors through inhibition of CD4+ and CD8+ T cell responses by promoting IL-10 and reducing cytotoxic responses in IFNγ- and IL-17A- dependent mechanisms." (PMID 33042110, 2020).
intestinal disease (10 papers, 2012 to 2025). "Furthermore, tofacitinib treatment reduced C. jejuni-induced intestinal disease and IFNγ production by human immune cells in humanized mice, collectively suggesting that JAK/STAT pathway inhibition does not compromise protection against C. jejuni." (PMID 40614970, 2025). "Furthermore, tofacitinib suppressed IFNγ production and ameliorated intestinal disease in humanized mice." (PMID 40614970, 2025). "Specifically, CEC-1 (ST129) or SWW33 (ST375)-colonized mice developed severe intestinal disease characterized by increased production of the pro-inflammatory cytokines granulocyte-macrophage colony-stimulating factor (GM-CSF), interleukin-6 (IL-6), and interferon-gamma (IFN-γ)." (PMID 30356663, 2018). "Inhibition of IL17A and IL17F in the absence of IFNγ partially protected mice from developing intestinal disease." (PMID 29416538, 2018). "Furthermore, a negative TST is relatively common in patients with disseminated TB, which explains why T-cell based interferon gamma release assays (IGRAs) have increasingly replaced TST in the differential diagnosis of ITB and other intestinal disorders, particularly CD." (PMID 25346193, 2014).
vasculopathy (10 papers, 2012 to 2025). "Mouse iTreg generated by IFNγ-conditioning of non-regulatory CD4+ T cells in the presence of alloantigen not only prevented the acute rejection of skin and islet allografts, but also the development of chronic allograft dysfunction (CAD)-associated vasculopathy of an arterial transplant." (PMID 22905732, 2012).
CNS tumors (9 papers, 2007 to 2023). "As mutational burden alone has not been a strong predictor, other groups have investigated specific somatic mutations, such as the interferon-gamma pathway that may portend a decreased response to checkpoint inhibition in non-CNS tumors." (PMID 30568917, 2018). "IFNγ-mediated induction of IDO1 was strongly reduced by mTOR inhibition with rapamycin suggesting that functional relationship between mTOR and IDO1 might be specific of MB among CNS tumors." (PMID 27174915, 2016).
neurodevelopmental disorder (9 papers, 2015 to 2025). A behavioral and cognitive disorder with onset during the developmental period that involves impaired or aberrant development of intellectual, motor, or social functions. "Using a human cellular model, we recently demonstrated that acute exposure to interferon-γ (IFNγ) recapitulates molecular and cellular phenotypes associated with neurodevelopmental disorders." (PMID 36186864, 2022). "Our findings further support a possible link between IFNγ exposure in immature glutamatergic neurons and cellular phenotypes associated with neurodevelopmental disorders, although further work is needed to understand the mechanistic basis of this link." (PMID 36186864, 2022). "This study builds on our previous work by showing that IFNγ-mediated disruption of relevant synaptic proteins can occur at early stages of neuronal development, potentially contributing to neurodevelopmental disorder phenotypes." (PMID 36186864, 2022). "A previous study from our group found increased maternal mid-gestation serum levels of interferon gamma (IFNγ), IL-4, and IL-5 in 84 mothers of children diagnosed with ASD compared to mothers of children from the general population with no known neurodevelopmental disorders (P. E)." (PMID 33327930, 2020).
brain diseases (7 papers, 2013 to 2025). "In the context of brain disease or injury, such as SE, inflammatory factors interferon gamma or tumor necrosis factor alpha activate microglia and increase their proliferation in response to damage." (PMID 41300233, 2025).
head and neck tumor (4 papers, 2008 to 2026). "Longitudinal, cumulative concentration assessment of CXCL10 and IFNγ from a representative human head and neck tumor resection showed an increased production rate with αCD3/αCD28 stimulation for both cross-well and sequential treatment experiments." (PMID 40791544, 2025).
hematologic cancers (4 papers, 2016 to 2025). "Somatic mutations in JAK1, required for immune cell signaling in response to interferon gamma (IFNγ), have been associated with several non-hematopoietic and hematopoietic cancer cell types but pathogenic mechanisms remain largely unexplored." (PMID 31552026, 2019).
peripheral neuropathy (4 papers, 2013 to 2025). A disorder affecting the peripheral nervous system. "Peripheral neuropathy in NOD-B7-2KO mice is dependent on interferon-gamma (IFN-γ)-producing CD4+ T cells that include autoreactive CD4+ T cells specific for peripheral nerve antigens such as myelin protein zero (P0)." (PMID 23850635, 2013).
connective tissue disease (3 papers, 2016 to 2025). "From the thymus data, network 4 showed connective tissue disorders, immunological disease, and inflammatory disease, included 26 genes, and showed a network with IFNG as a central node." (PMID 27463006, 2016).
musculoskeletal diseases (2 papers, 2016). "We demonstrated that the immunocompetent mouse model of CIOA was relevant to test the therapeutic efficacy of xenogeneic eASCs for OA and confirmed that IFNγ-primed eASCs may have a therapeutic value for musculoskeletal diseases in veterinary medicine." (PMID 27729913, 2016).
IFNG also shares sentences with these, for which no sentence is quoted: multiple myeloma (36 papers); nasal polyps (26); viral diseases (25); chronic periodontitis (22); autoimmune uveitis (19); idiopathic pulmonary fibrosis (18); systemic sclerosis (17); diphtheria (15); enteritis (14); Hypercholesterolemia (14); encephalomyelitis (13); pancreatitis (13); chronic myeloid leukemia (12); chronic rhinosinusitis (12); hyperferritinemia (12); pulmonary edema (12); chronic asthma (11); myasthenia gravis (11); cerebral toxoplasmosis (10); esophageal squamous cell carcinoma (10); filariasis (10); prostatitis (10); sporotrichosis (10); viral pneumonia (10); Arrhythmia (9); bipolar disorder (9); blood cancer (9); Burkitt lymphoma (9); chronic mucocutaneous candidiasis (9); diabetic nephropathy (9).
A further 778 diseases each share a sentence with IFNG in 9 papers or fewer.